RNU6-1327P (RNA, U6 small nuclear 1327, pseudogene)
Gene: Small nuclear RNA gene on chromosome 9 (558,826 to 558,930, forward strand). Ensembl gene ENSG00000202172.
Homologues: Orthologues: chimpanzee U6 (100% identical), macaque U6 (92% identical). Paralogues in human: RNU6-43P (90% identical), RNU6-11P (89% identical), RNU6-19P (89% identical), RNU6-24P (89% identical), RNU6-37P (89% identical), RNU6-1075P (88% identical), RNU6-1151P (88% identical), RNU6-1243P (88% identical), RNU6-12P (88% identical), RNU6-1329P (88% identical), RNU6-13P (88% identical), RNU6-23P (88% identical), and 1287 more.